BRAF (B-Raf proto-oncogene, serine/threonine kinase)
Diseases named in the same sentence as BRAF in open-access papers (continued):
Sharing a sentence is not in itself a finding about the gene and the disease.
melanoma (continued). "The screening procedure identified a BRAF inhibitor active in melanoma Malme-3M cells (IC50 = 0.85 ± 0.19 μM) but virtually ineffective in thyroid 8505C and KTC-1 cancer cells (IC50 > 10 μM, not shown)." (PMID 26942566, 2016). "Our data overall suggest that TGFBR1 inhibitors would reduce the metastatic burden in BRAF mutant melanoma by preventing invasion and/or outgrowth of metastatic colonies." (PMID 27835901, 2016). "BRAF V600E mutant (A375) human melanoma tumor cells were plated at a density of 2 × 105 cells/well on a 6 well plate and treated for 48 hours with complete medium supplemented with either 35 nM ixazomib, 15 nM ixazomib, 10 nM bortezomib, or 10% DMSO." (PMID 27783987, 2016). "Several molecular markers, e.g. such as BRAF expression in malignant melanoma, are well known to correlate with aggressiveness of the tumor and its prognosis." (PMID 27564260, 2016). "Because clinical responses to BRAF inhibitor treatment of BRAF mutant melanomas are generally incomplete, there is a compelling need to identify actionable mechanisms of intrinsic and rapidly appearing adaptive resistance to MAP Kinase pathway inhibition." (PMID 26673621, 2016). "The greater susceptibility to Prima-1 ± 3-BrPA in hypoxic mutant NRAS MelJuso melanoma (Summary), suggests that agents like Prima-1 + 3-BrPA, may help attenuate the frequent acquisition of resistance to targeted therapy against V600E BRAF-mutated tumors which acquire NRAS mutations." (PMID 27863474, 2016). "Studies have shown the increased expression of genes involved in TCA cycle, oxidative phosphorylation and ATP generation in melanomas with mutant BRAF treated with vemurafenib, an inhibitor of BRAF-V600E." (PMID 27285585, 2016). "Relief of profound crosstalk inhibition of HGFR signaling by drugs (or inhibitors) targeting BRAF attenuates the drug efficacy in BRAFV600E melanomas." (PMID 27590512, 2016). "In melanoma, the MAPK pathway can also be activated as a result of mutations in BRAF genes (e.g., BRAFV600E) or loss of neurofibromatosis type 1 (NF1) activity due to inactivating mutations." (PMID 27608486, 2016). "Here, we have used the ERK inhibitor SCH772984 as a tool to investigate the molecular determinants of resistance to ERK inhibition in BRAF-V600E melanomas and assessed the potential therapeutic value of co-targeting ERK and the Notch pathway." (PMID 27655717, 2016). "The addiction of mutant BRAF melanoma cells to signalling through TGFBR1 suggests a potential novel therapeutic approach for mutant BRAF-driven cancers." (PMID 27835901, 2016). "In co-cultures of melanoma cell lines and human monocyte-derived dendritic cells, inhibition of BRAF and MEK restores compromised dendritic cell function." (PMID 27532019, 2016). "While BRAF mutant melanomas often respond to BRAF/MEK inhibition, in most cases the response is short lived." (PMID 26871475, 2016). "The identification of additional melanoma oncogenic mechanisms initiated by oncogenic BRAF will facilitate the development of more long-term effective therapeutic approaches." (PMID 27167340, 2016). "In support of this idea, inhibition of MEK or BRAF in melanoma correlated with reduced levels of immunosuppressive cytokines and an increase in infiltrating T cells." (PMID 27096871, 2016). "Though the effects of paradoxical ERK activation most often manifest as cuSCC induction, cases of NRAS-mutant leukemia and new primary BRAF wild-type melanomas have also been reported." (PMID 27028853, 2016). "To this purpose we compared OP-A-dependent cell death induction of A375 (BRAF V600E) with CHL-1 (BRAF wt) melanoma, and HaCaT (immortalised keratinocytes) cell lines." (PMID 27936075, 2016). "We observed that SGI-1776 also prevents melanoma tumor growth in vivo as a single agent and when combined with the BRAF inhibitor PLX4720." (PMID 27448973, 2016).
melanoma (continued). "We believe that the combination of BET inhibitors with a BRAF and/or an MEK inhibitor is a promising new strategy that warrants further preclinical and clinical development against BRAF‐mutant melanoma tumors." (PMID 27169980, 2016). "We employed RPPA to map the basal activation state and adaptive responses to BRAF inhibition on a broader range of signaling pathway proteins in our panel of 12 BRAFV600E melanomas as well as 4 BRAFwt melanomas." (PMID 26673621, 2016). "Here, we show that concurrent loss of PTEN and activation of the Notch pathway is associated with poor response to the ERK inhibitor SCH772984, and that co-inhibition of Notch and ERK decreased viability in BRAF-V600E melanomas." (PMID 27655717, 2016). "Because resistance to BRAF inhibitors in melanoma patients is almost always due to reactivation of the MAP Kinase pathway we expected that lapatinib would reinforce the effectiveness of PLX4720 on MAP Kinase pathway inhibition." (PMID 26673621, 2016). "One study demonstrated a synergistic relationship between metformin and vemurafenib in 7/8 BRAF wild-type/NRAS mutant melanoma cell lines tested." (PMID 27447557, 2016). "Next, we examined these responses in SKMEL5 and G361 cells, because these BRAF mutant melanoma cells are intrinsically resistant to BRAF inhibitors and are ∼10 fold less sensitive to PLX4720 than A375 and Colo829." (PMID 26365896, 2016). "As a control, 10 short-term melanoma cell cultures from tumors with wt BRAF were characterized for responsiveness to the four inhibitors." (PMID 26678033, 2016). "Cumulatively, based on these findings, we propose a model detailing the rationale for the dual targeting of AURKA and MAPK signaling in melanomas harboring the constitutively active BRAF(V600E) or NRAS (Q61R)." (PMID 26962685, 2016). "We observed that DETS is effectively down-regulating the expression of oncogenic BRAF which is shown to be mutated and activated in A375 cells and Brn-2, a molecule highly over-expressed in BRAF mutant melanoma cells and." (PMID 27148169, 2016). "The Cancer Genome Atlas Network revealed that specific genomic mutations and alterations are expressed not only in one certain histopathological defined tumor (i.e. BRAF in melanoma) but also in tumors deriving from other origins." (PMID 28050231, 2016). "In melanoma cells, the activation of the MAPK pathway through BRAF mutations leads to the downstream production of several cytokines that promote tumor growth, invasiveness and immune evasion through their autocrine and paracrine effects." (PMID 26684239, 2016). "Acquired resistance to BRAF inhibitors in melanoma can be overcome by targeting MEK and IGF-1R/PI3K simultaneously." (PMID 27764776, 2016). "We generated drug‐resistant cell variants in vitro from human BRAF‐mutant melanoma cell lines MEL‐HO, COLO‐38, SK‐MEL‐37, 1520 and from primary melanoma cells freshly isolated from two patients." (PMID 26564811, 2016). "The remaining three patients all had stage IV malignant melanoma, one of whom (# 12) was BRAF V600 positive." (PMID 27525031, 2016). "The ability of ixazomib to inhibit cell proliferation of BRAF V600E mutant human melanoma was evaluated." (PMID 27783987, 2016). "WNT-5A binding to FZD7 activates prosurvival PI3K/AKT cascade in human melanoma cells which can account for the resistance of these cells to BRAF inhibitors." (PMID 26514730, 2016). "These include not only the ~50% of BRAF mutations, but also >25% NRAS mutations and ~14% of melanomas with mutations in the RAS suppressor NF1." (PMID 27200346, 2016). "Blockade of BRAF in the BRAFV600E melanoma lines resulted in a drop in activating phosphorylations throughout the MAP Kinase pathway, including the transcription factor ELK1 and downstream kinases p90RSK and MSK1." (PMID 26673621, 2016). "This demonstrates that exogenous CSF dramatically shortens the kinetics of BRAF‐mutant melanoma cell response to PLX4720." (PMID 26414886, 2016).
melanoma (continued). "Patients with BRAF mutant metastatic melanoma were significantly younger at diagnosis of the first distant metastasis (mean = 59.1 years; SD=14.9) compared to the patients with BRAF wild-type melanoma (mean= 65.4 years; SD= 14.5; P= 0.0001, Student's t-test)." (PMID 27191502, 2016). "In BRAF inhibitor-resistant melanoma cells, JUN was characterized as a mediator of upregulated PD-L1 expression." (PMID 27648299, 2016). "To examine possible synergy of BET and BRAF inhibitor combinations in vivo, we assessed single agent and combination therapy in a preclinical xenograft model of BRAF‐mutant melanoma." (PMID 27169980, 2016). "Excitingly, whereas both PLX4032 and the FOXM1-S704 DRI peptide individually reduced EM5 melanoid viability, their combination decreased viability to levels below background, indicating that FOXM1-S704 can be additive to BRAF inhibition against human melanoma." (PMID 26279295, 2016). "This study investigated the interaction between RT3D and radiotherapy in melanoma cell lines with a BRAF mutant, Ras mutant or BRAF/Ras wild type genotype." (PMID 27384486, 2016). "We asked if the double-mutated cell cultures consisted of two exclusive populations of cells (one with BRAF and another with NRAS mutations), or if both mutations were present in single melanoma cells." (PMID 27791198, 2016). "Specifically targeting melanocytes by using the tyrosinase promoter resulted in the sole formation of melanomas, which were responsive to selective BRAF inhibition." (PMID 27999416, 2016). "Vemurafenib and dabrafenib are currently approved for BRAF V600E-positive malignant melanomas, but single-agent activity in BRAF V600E- positive NSCLC is limited." (PMID 27938382, 2016). "Respectively 50%, 30%, 33% and 20% of BRAF-, NRAS-, c-KIT-mutated or wild type melanomas were successfully engrafted." (PMID 26909610, 2016). "Accordingly, the viability of melanoma cells freshly isolated from a patient at 72h with a wild-type BRAF and NRAS status also largely decreased upon NS1 treatment." (PMID 27756874, 2016). "Here we identify a novel small molecule compound which sensitized BRAF wild-type melanoma cells to vemurafenib." (PMID 27447557, 2016). "In BRAF mutant melanoma cells, BRAF is the driver of cellular signaling — the prerequisite to BRAF-targeted therapy." (PMID 26977879, 2016). "An initial phase I trial of patients with BRAF V600E-mutant melanoma examined escalating doses of dabrafenib in 184 patients (156 patients with MM and 28 with non-melanoma solid tumors)." (PMID 26767073, 2016). "The median intracranial PFS was 4.6 months and median OS was 7.5 months, thus demonstrating that vemurafenib is highly active in mutant BRAF melanoma, with intracranial activity evident." (PMID 27598148, 2016). "In these reports, untreated (BRAF inhibitor-naive) melanoma cells were found to transition between a ‘proliferative’ and an ‘invasive’ state." (PMID 27648299, 2016). "We investigated the regulation of TERT expression in melanoma cell lines and our results show that promoter mutations render TERT expression dependent on MAPK activation due to oncogenic BRAF or NRAS mutations." (PMID 27449293, 2016). "In fact, the use of BRAF inhibitors have been approved to treatment of melanoma and, although recurrence has been reported, most of the cases are associated with the plasticity of the tumors to reactivate MAPK or upregulate the alternative pathway, PI3K/Akt44." (PMID 26898917, 2016). "Recently, it was reported that copper plays a role in BRAF signalling and tumorigenesis in melanoma, demonstrating the importance of this metal ion in cancer progression." (PMID 27374085, 2016). "Previous work carried out in our lab combining GLV-1h68 (oncolytic vaccinia virus) and RT showed a synergistic effect in BRAF mutant melanoma that is mediated through JNK and TNFα signalling." (PMID 27384486, 2016).
melanoma (continued). "TGFβ signalling promotes migration of BRAF-transformed melanocytes in in vitro organotypic skin cultures and is involved in metastasis of mouse melanoma cells to the bone through expression of tissue-specific genes known to promote bone osteolysis." (PMID 27835901, 2016). "Of note, inhibition of HSP90 by the inhibitor XL888 has been reported to potently sensitize mutant BRAF melanoma cells to BRAF inhibitors through diverse mechanisms." (PMID 27391062, 2016). "The WM1366 (BRAF wild-type) human melanoma tumor cell line was used and cells were plated on a six well plate at a density of 2 × 105 cells/well." (PMID 27783987, 2016). "For the studies reported here, we used BRAF mutant A375 and Colo829 melanoma cell clones (A375/R and Colo829/R respectively) that were over 100‐fold less sensitive to the BRAF inhibitor PLX4720 than their respective parental cells." (PMID 26365896, 2016). "Melanoma patients treated with oncogenic BRAF inhibitors can develop cutaneous squamous cell carcinoma (cSCC) within weeks of treatment, driven by paradoxical RAS/RAF/MAPK pathway activation." (PMID 27558455, 2016). "Combination treatment with ixazomib and IFN-α resulted in a greater decrease in cell proliferation than either agent alone in BRAF V600E mutant (A375) melanoma cell line." (PMID 27783987, 2016). "The change in fluorescence can be monitored by live cell microscopy, thereby providing a dynamic read‐out of ERK/MAP kinase activity in BRAF‐mutant melanoma cells." (PMID 26414886, 2016). "Gossypol, a cottonseed extract, has shown effective therapeutic action against BRAF V600E melanoma with resistance to BRAF inhibitors." (PMID 26884744, 2016). "In fact, the expression of RAC1 P29S in sensitive BRAF-mutant melanoma cell lines confers resistance to treatment with RAF inhibitors." (PMID 26860319, 2016). "Intrinsic resistance to BRAF inhibitors prevents ∼20% of melanoma patients with BRAF-mutant tumors from achieving clinical benefit from this type of target therapy and represents a major clinical issue [31, for review]." (PMID 26678033, 2016). "Analysis of samples from patients with recurrent disease has provided considerable insight into the mechanisms by which BRAF mutant melanomas ultimately achieve resistance to BRAF inhibitors." (PMID 26673621, 2016). "Primary cross-resistance was confirmed in an independent set of 23 BRAF-mutant short-term melanoma cell cultures." (PMID 26678033, 2016). "Our data raise the possibility that MEK inhibitor can be used to treat some BRAF wild-type melanomas if combined with a cardiac glycoside." (PMID 27545456, 2016). "Inhibiting HDAC in melanoma cells improved the response to BRAF inhibitors, resulting in growth arrest and increased apoptosis." (PMID 26927180, 2016). "Prolonged treatment with BRAF inhibitors induces WNT-5A expression in melanoma cells and contributes to the development of resistance to BRAF inhibitor-induced apoptosis." (PMID 26514730, 2016). "In humans, mutations in BRAF, most notably the BRAFV600E mutation, are highly associated with a large number of cancers, e.g. 60% of melanomas harbor BRAF alterations." (PMID 27348307, 2016). "The identification of genetic drivers of melanoma has led to the development of small-molecule inhibitors inhibitors (e.g. vemurafenib, dabrafenib) (BRAFi), which selectively target mutant BRAF." (PMID 27835901, 2016). "KRAS amplification was also observed in a tumor at recurrence in a melanoma patient treated with combination BRAF and MEK inhibitor therapy." (PMID 27081080, 2016). "A BRAF-V600E-mutant melanoma obtained from the right chest wall of a patient was grown orthotopically in the right chest wall of nude mice to establish a PDOX model." (PMID 27690220, 2016). "Wnt5a was found to be highly upregulated in a subset of BRAF inhibitor (BRAFi)-resistant melanoma tumors and in BRAFi-resistant melanoma cells derived in vitro." (PMID 27571105, 2016).
melanoma (continued). "The experiments presented here support the combination of the BET inhibitor JQ1 with the BRAF inhibitor Vemurafenib for the treatment of BRAF‐mutant melanoma patients." (PMID 27169980, 2016). "Here, we studied four BRAFi and generated ERK activation profiles in conjunction with inhibition profiles against BRAF-mutant A375 melanoma cells." (PMID 27028853, 2016). "SKI thus helps to maintain the MITF homeostasis downstream of BRAFV600E required for BRAF-driven melanoma development." (PMID 26977879, 2016). "For example, BRAFi enhance PD‐L1 expression on melanoma cells 8, providing an argument for combining therapies that target both BRAF and the PD‐1 pathway." (PMID 26564811, 2016). "Here we show that lung fibroblasts reduce melanoma sensitivity to the BRAF inhibitor (BRAFi) vemurafenib only if the two cell types are in close proximity." (PMID 26918352, 2016). "Approximately one and half years later, he presented with recurrence of his melanoma with right groin lymph node involvement and bilateral small lung metastases, BRAF V600 wild-type." (PMID 27777775, 2016). "As for Rapamycin, the growth suppressive activities of the remaining 10 shortlisted hits were evaluated against established human melanoma cell lines that carry activating mutations in RAS (WM1361, MM485, WM852, and DO4) or BRAF (A375, 501Mel, and WM2664)." (PMID 27248171, 2016). "The ability of ixazomib to induce apoptosis of BRAF V600E mutant human melanoma cells was evaluated via annexin V/ propidium iodide (PI) staining and flow cytometric analysis." (PMID 27783987, 2016). "Patients with late stage BRAF mutant melanomas administered vemurafenib, a BRAF inhibitor, show significant tumour regression and increased survival." (PMID 26927180, 2016). "Even though the mechanisms of resistance are diverse, the MAPK pathway is frequently reactivated in melanomas resistant to these drugs, underscoring the addiction of BRAF mutant melanomas to this pathway." (PMID 27655717, 2016). "Together these pre-clinical and clinical data suggest that combined treatment with ixazomib and IFN-α represents a novel treatment strategy for inducing synergistic apoptotic tumor cell death in BRAF V600E mutant melanoma." (PMID 27783987, 2016). "Over half of BRAFV600E melanomas display intrinsic resistance to BRAF inhibitors, in part due to adaptive signaling responses." (PMID 26673621, 2016). "In a xenograft mouse model of BRAF‐mutant melanoma, combination therapy profoundly impaired tumor growth and prolonged animal survival compared to single agent groups." (PMID 27169980, 2016). "This is in line with two other studies using PCR based methods, where BRAF V600mut ctDNA was detected in plasma of 73–84 % of BRAF V600 mutant melanoma patients." (PMID 27095081, 2016). "Pharmacological inhibition of the TGFBR1 blocked the clonogenicity of human mutant BRAF melanoma cells through SMAD4-independent inhibition of mitosis, and also inhibited metastasis in xenografted zebrafish." (PMID 27835901, 2016). "Vemurafenib, a BRAF kinase inhibitor, has been shown to be effective in BRAF V600E mutation-positive malignancies, such as NSCLC and melanoma, as well as in several case reports of Erdheim-Chester disease." (PMID 27995058, 2016). "Knock-down of endogenous WNT-5A decreases melanoma cell proliferation and sensitizes them to BRAF inhibitor-induced cell death." (PMID 26514730, 2016). "Although MAPK pathway inhibitors are becoming a promising anticancer strategy, they are insufficient to fully eliminate cancer cells and their long-term efficacy is strikingly limited in patients with BRAF-mutant melanomas." (PMID 27250023, 2016). "Up-regulation of the expression of EGF-R, PDGFRβ, AXL and IGF-1R in melanoma cells that have developed resistance to BRAF V600E targeted therapy results in reactivation of the MAPK and the PI3K/AKT pathways." (PMID 27102439, 2016).